ABHD11 (abhydrolase domain containing 11)
Description:
Catalyzes the hydrolysis of diacylglycerol in vitro and may function as a key regulator in lipid metabolism, namely by regulating the intracellular levels of diacylglycerol. 1,2-diacyl-sn-glycerols are the preferred substrate over 1,3-diacyl-sn-glycerols (By similarity). The enzyme hydrolyzes stearate in preference to palmitate from the sn-1 position of 1,2-diacyl-sn-glycerols (By similarity). Maintains the functional lipoylation of the 2-oxoglutarate dehydrogenase complex (OGDHc) through its interaction with the OGDHc by preventing the formation of lipoyl adducts. In addition, is also required for the expansion and differentiation of embryonic stem cells (ESCs) (By similarity).
Synonyms: WBSCR21; PP1226
Tractability: Small molecule: a high-quality ligand is known. PROTAC: ubiquitination databases record sites on it; its protein half-life has been measured.
Target class: Enzyme; Hydrolase
Chemical probes: ML-226
Gene: Protein-coding gene on chromosome 7 (73,736,091 to 73,738,863, reverse strand). Ensembl gene ENSG00000106077.
Subcellular location: Mitochondrion; Mitochondrion matrix
Subcellular location (Human Protein Atlas): Mitochondria
Gene Ontology:
Molecular function: lipase activity; carboxylic ester hydrolase activity; diacylglycerol lipase activity
Biological process: lipid metabolic process
Cellular component: mitochondrial matrix; mitochondrion; oxoglutarate dehydrogenase complex
Genetic constraint (gnomAD): Loss-of-function variants: 26 observed, 30.22 expected, observed/expected ratio (o/e) 0.86, 90% interval 0.63 to 1.19. The upper end of that interval is the gene's LOEUF score, 1.19, which puts it in group 5 of 6, group 1 being the genes least tolerant of losing a copy. Missense variants: 381 observed, 436.06 expected, observed/expected ratio (o/e) 0.87, 90% interval 0.8 to 0.95. Synonymous variants: 169 observed, 170.13 expected, observed/expected ratio (o/e) 0.99, 90% interval 0.88 to 1.13.
Homologues: Orthologues: chimpanzee ABHD11 (100% identical), macaque ABHD11 (88% identical), guinea pig ABHD11 (79% identical), pig ABHD11 (77% identical), rabbit ABHD11 (77% identical), dog ABHD11 (75% identical), mouse Abhd11 (70% identical), rat Abhd11 (66% identical), zebrafish abhd11 (47% identical), tropical clawed frog abhd11 (47% identical), Caenorhabditis elegans abhd-11.2 (33% identical), Drosophila melanogaster CG2059 (31% identical), and 1 more. Paralogues in human: EPHX2 (23% identical), MEST (23% identical), ABHD6 (19% identical), EPHX3 (18% identical), ABHD14A (17% identical), EPHX4 (17% identical), ABHD5 (16% identical), SERHL2 (15% identical), BPHL (15% identical), ABHD8 (14% identical), ABHD4 (13% identical), ABHD14B (12% identical).
Diseases named in the same sentence as ABHD11 in open-access papers:
ABHD11 is named in the same sentence as 23 diseases in open-access papers, as found by Europe PMC text mining. Sharing a sentence is not in itself a finding about the gene and the disease. The quoted sentences say what the papers report.
type 1 diabetes (3 papers, 2022 to 2025). "Importantly, using a murine model of accelerated type 1 diabetes (T1D), we show that targeting ABHD11 suppresses cytokine production in antigen-specific T cells and delays the onset of diabetes in vivo." (PMID 40166327, 2025). "Importantly, using murine models of accelerated type 1 diabetes (T1D), we show that targeting ABHD11 suppresses cytokine production in antigen-specific T-cells and delays the onset of diabetes in vivo in female mice." (PMID 41184294, 2025).
autoimmune disease (2 papers, 2025). A disorder resulting from loss of function or tissue destruction of an organ or multiple organs, arising from humoral or cellular immune responses of the individual to their own tissue constituents. "Together, these data demonstrate the potential of modulating ABHD11 function for therapeutic benefit in T cell-mediated autoimmune disease." (PMID 40166327, 2025). "Together, these findings encourage targeting ABHD11 to alleviate T cell-mediated autoimmune disease, thus providing the precedent for further pre-clinical studies." (PMID 40166327, 2025). "Together, these findings demonstrate that ABHD11 inhibition retains its suppressive effect on T cell function in patients with autoimmune disease, including those present at the site of inflammation." (PMID 40166327, 2025). "This highlights the exciting potential of manipulating ABHD11 function for therapeutic benefit in T-cell-mediated autoimmune disease, where reversing the hyper-activation and -function of pathogenic T-cells would be valuable." (PMID 41184294, 2025).
Autoimmunity (2 papers, 2025). The occurrence of an immune reaction against the organism's own cells or tissues. "Our manuscript supports the further development of ABHD11 inhibitors as a treatment for T cell-mediated autoimmunity." (PMID 40166327, 2025). "Crucially, ABHD11 inhibition retained its suppressive effect on T cell function in multiple settings of autoimmunity." (PMID 40166327, 2025). "Crucially, ABHD11 inhibition retained its suppressive effect on T-cell function in two human cohorts of autoimmunity." (PMID 41184294, 2025). "Crucially, ex vivo pharmacological inhibition of ABHD11 suppressed T cell function in two autoimmune patient cohorts, whilst also attenuating disease activity in a murine model of autoimmunity in vivo." (PMID 40166327, 2025). "However, the importance of ABHD11 in regulating T cell metabolism and function – and thus, the downstream implication for autoimmunity – is yet to be explored." (PMID 40166327, 2025). "However, beyond its role in maintaining the function of α-KGDH22, the function of ABHD11 in human T cells remains unknown, and as such, its significance in autoimmunity has yet to be explored." (PMID 40166327, 2025).
breast carcinoma (2 papers, 2019 to 2020). "In addition, ABHD11 is a potential biomarker of lung adenocarcinoma, and is linked to breast cancer malignancy." (PMID 32733886, 2020). "In this study, we detected three mitochondrial proteins (CPS1, ATAD3A/ATAD3B, and ABHD11) and one lysosomal protein (cathepsin D) with different expressions in paclitaxel-resistant MCF7/PacR breast cancer cells compared to paclitaxel-sensitive MCF7 breast cancer cells." (PMID 31248089, 2019).
lung adenocarcinoma (2 papers, 2020). A carcinoma that arises from the lung and is characterized by the presence of malignant glandular epithelial cells. "ABHD11, the mammalian homolog to KmYME, has high expression in metabolically active tissues and is related to many diseases such as Williams-Beuren syndrome and lung adenocarcinoma, though the causal connection of ABHD11 to these diseases is not clear." (PMID 32850717, 2020).
Obesity (2 papers, 2020 to 2022). Accumulation of substantial excess body fat. "Taken together, these observations revealed that ABHD11 KO mice are resistant to obesity induced by HFD and present normal blood parameters." (PMID 32579589, 2020). "To determine if this enzyme plays a role in obesity, mice deprived of ABHD11 (KO ABHD11) were phenotyped in a high fat diet (HFD) study and we have shown that the absence of ABHD11 leads to resistance to weight gain." (PMID 32579589, 2020). "Transcriptomic analysis performed on the mice livers confirm the absence of diet-induced obesity and metabolic deregulation in animals with deleted ABHD11 gene, suggesting a role of ABHD11 in lipid absorption in the gut." (PMID 32579589, 2020).
rheumatoid arthritis (2 papers, 2025). A chronic, systemic autoimmune disorder characterized by inflammation in the synovial membranes and articular surfaces. "α/β-hydrolase domain-containing protein 11 (ABHD11) is a mitochondrial hydrolase, and its expression in CD4 + T-cells has been linked to remission status in rheumatoid arthritis." (PMID 41184294, 2025). "α/β-hydrolase domain-containing protein 11 (ABHD11) is a mitochondrial hydrolase that maintains the catalytic function of α-ketoglutarate dehydrogenase (α-KGDH), and its expression in CD4+ T cells has been linked to remission status in rheumatoid arthritis (RA)." (PMID 40166327, 2025).
Williams-Beuren syndrome (2 papers, 2020). "ABHD11 is one of ~26 genes included in the 7q11.23 hemizygous deletion of Williams-Beuren syndrome, a rare multisystem disorder often characterised by developmental and cardiac abnormalities." (PMID 32792488, 2020).
breast tumors (1 paper, 2017). "The expression of ABHD11, ADORA2B, E2F1, EZH2, PAICS, SFN and SH3GL1 was significantly higher in grade III than in grade I breast tumors." (PMID 28411283, 2017).
Hyperinsulinemia (1 paper, 2020). An increased concentration of insulin in the blood. "ABHD11 KO mice under HFD did not exhibit such DIO-dependent hyperinsulinemia." (PMID 32579589, 2020).
lung carcinoma (1 paper, 2020). "In consideration of the high expression of ABHD11 in lung cancer and the key roles of both elevated de novo lipid biosynthesis and increased glycolysis in cancer, it is crucial to establish whether ABHD11 contributes to malignancy and whether its inhibition can block tumor growth." (PMID 32733886, 2020).
cancer (5 papers, 2019 to 2025). A tumor composed of atypical neoplastic, often pleomorphic cells that invade other tissues. "Within cancer cells, ABHD11 inhibition predominantly leads to inactivation of 2-OGDDs involved in hypoxia-inducible factor (HIF) signaling and DNA methylation." (PMID 40664791, 2025). "Here, we show that impaired OGDHc activity (via ABHD11 inhibition) in human CD8+ lymphocytes has distinct effects from those observed in cancer cells, with the perturbed TCA cycle driving synthesis of unsaturated fatty acids, rather than the accumulation of 2-HG that inhibits 2-OGDDs." (PMID 40664791, 2025). "Germline mutations in LIAS, LIPT2 and LIPT1 result in impaired PDHc and OGDHc activity, but ABHD11 loss did not significantly alter DLAT lipoylation in several cancer lines." (PMID 32792488, 2020). "The ABHD11 locus also encodes for long non-coding RNA, termed as ABHD11-AS1 (antisense 1), whose expression is increased in gastric, colorectal, pancreatic and endometrial cancer." (PMID 31248089, 2019). "Therefore, we explored whether ABHD11 inhibition altered OGDHc activity in CD8+ T cells, as observed in cancer cell lines." (PMID 40664791, 2025).
tumor (3 papers, 2020 to 2024). "Moreover, we demonstrate that ABHD11 inhibition allows 2-OG metabolism to be modulated in multiple cells and in a reversible manner, with potential broad implications for altering cell fate-decisions and manipulating 2-OG abundance in tumours." (PMID 32792488, 2020).
genetic disease (1 paper, 2019). "ABHD11 is localized in the locus that is deleted in Williams–Beuren syndrome, which is a multisystemic genetic disease." (PMID 31248089, 2019).
metabolic disorders (1 paper, 2020). "The viability of the KO mice combined with their phenotype and molecular features suggest that modulation of ABHD11 or of its signaling pathway could provide an attractive avenue to engage into drug screening and develop new therapeutic agents for metabolic disorders." (PMID 32579589, 2020).
ABHD11 also shares sentences with these, for which no sentence is quoted: diabetes (2 papers); breast adenocarcinoma (1); colon adenocarcinoma (1); hepatocellular carcinoma (1); Huntington disease (1); Insulin resistance (1); neurodegenerative disease (1); type 2 diabetes (1).